APOC2 (apolipoprotein C2)
Diseases named in the same sentence as APOC2 in open-access papers (continued):
Sharing a sentence is not in itself a finding about the gene and the disease.
tumor (26 papers, 2019 to 2026). "APOC2, a regulator of fatty acid transport and lipid metabolism, has been associated with tumor formation, invasion, and metastasis, and its high expression correlates with poor prognosis in CRC." (PMID 41303528, 2025). "Ligands participating in these interactions are known immunosuppressive molecules (e.g., Tgfb1, Il1b), pro-angiogenic factors (e.g., Vegfa), or other genes associated with tumor progression (e.g., Fn1, Apoe, Apoc2)." (PMID 40216735, 2025). "miR-4510; APOC2• Association of miR-4510 levels with tumor location, tumor size, mitotic index and risk classification." (PMID 32972022, 2020). "APOC2 has been identified as a potential diagnostic biomarker for cancer detection and as an auxiliary prognostic marker or marker for immunotherapy in certain tumor types." (PMID 39869563, 2025). "The remaining three subpopulations, namely MLB (86.0%), GPAM+ macrophages (74.2%), and APOC2+ macrophages (87.7%), were significantly enriched in the pCR group, suggesting potential anti-tumor or ICB-sensitizing roles." (PMID 41514936, 2026). "APOC2 has been reported to promote tumor cell proliferation and invasion in gastric and hematological malignancies." (PMID 41296440, 2025). "In non-small cell lung cancer (NSCLC), lactylation of apolipoprotein C-II (APOC2) at the K70 site elevates extracellular lipolysis and levels of free fatty acids, contributing to tumor cell metastasis and immunotherapy resistance." (PMID 40421024, 2025). "A subsequent unpaired analysis of 533 ccRCC tumor samples and 72 normal kidney tissues further confirmed that APOC2 mRNA levels were markedly higher in ccRCC tissues compared to normal counterparts." (PMID 41296440, 2025). "Our findings identify APOC2 as a novel oncogenic factor in ccRCC that promotes tumor progression, at least in part, via activation of the JAK/STAT pathway." (PMID 41296440, 2025). "We demonstrate that APOC2 is markedly upregulated in tumor tissues and cell lines and correlates with unfavorable prognosis." (PMID 41296440, 2025). "We also found that using an Anti‐APOC2K70‐lac antibody can neutralize extracellular APOC2, and when paired with anti‐PD‐1 treatment, it significantly inhibited tumor growth." (PMID 38981044, 2024). "To investigate the mechanisms orchestrating cancer stemness and tumour development, we analysed the transcriptional differences between differentiated (Krt20+Apoc2+Fabp2+) and stem (Lgr5+Cd44+Sox9+) cancer cells within tumours." (PMID 38658753, 2024). "miR-4510 demonstrated its tumour suppressor effects by targeting and inhibiting apolipoprotein C-II (ApoC2) expression, and also decreased the activity of AKT, ERK1/2, MMP2 and MMP9." (PMID 36765536, 2023). "The results revealed that PHGDH and NR1I2 genes exhibited low expression in HCC tumor tissues (P-value < 0.001) while APOC2 genes were highly expressed in HCC tumor tissues (P-value < 0.01)." (PMID 37008043, 2022). "The relationship between lipid metabolism and cancer has been proven, but there are relatively few studies on the role of APOC2 in tumor." (PMID 34459127, 2021). "CD36 has been reported to regulate PI3K/AKT signaling in tumor progression, but the exact interaction between APOC2 and CD36 as well as subsequent effect on PI3K/AKT/mTOR signaling in GC have not been investigated." (PMID 34459127, 2021). "Taken together, these data suggested that APOC2 cooperated with CD36 to promote tumor progression and PM in GC." (PMID 34459127, 2021). "A different group highlighted that miR-4510 downregulation, as normally is observed in GIST cells, promotes GIST progression including tumor growth, invasion and metastasis through the increase in apolipoprotein C-II (APOC2), shown to be an miR-4510 target." (PMID 32972022, 2020). "APOC2 may function in a similar manner, possibly via interaction with lipid transport receptors or cytokine receptors in the tumor microenvironment." (PMID 41296440, 2025).
tumor (continued). "Moreover, APOC2 expression correlates with poor prognosis in multiple tumor types, underscoring its clinical relevance." (PMID 41296440, 2025). "Recent findings suggest that APOC2 may influence tumor behavior by modulating oncogenic signaling pathways, including inflammation and lipid-driven proliferation." (PMID 41296440, 2025). "Treatment with an STAT3-specific activator partially reversed the tumor-suppressive effects of APOC2 knockdown, supporting the hypothesis that JAK2/STAT3 is a key downstream effector of APOC2." (PMID 41296440, 2025). "In summary, APOC2 exhibits potential tumor-promoting properties in ccRCC." (PMID 41296440, 2025). "Single-cell RNA sequencing and spatial transcriptomics could help delineate APOC2 expression in different cellular compartments of the tumor and its impact on immune crosstalk." (PMID 41296440, 2025). "In addition, the frequencies of tumor necrosis factor (TNF)‐α+interferon (IFN)‐γ+, CD62L‐CD44+, and CD69+ tumor‐infiltrating CD8+ T cells were increased by anti‐PD‐1 mAb in tumors with APOC2‐K70R." (PMID 38981044, 2024). "The inhibition of APOC2 has been shown to delay tumor progression." (PMID 38067270, 2023). "During the remodeling of the immunosuppressive CD8-Tef-APOC2 subpopulation into a tumor-killing CD8-Tef-GZMA subpopulation, the metabolic pattern of exogenous lipid metabolism was gradually replaced by the metabolic patterns of amino acid and endogenous lipid synthesis." (PMID 36497182, 2022). "APOC2 may influence tumor biology via lipid metabolism and inflammation." (PMID 41438620, 2025). "As APOC2 is closely associated with lipid metabolism, variations in dietary lipid intake or metabolic state could potentially modulate the APOC2–JAK/STAT axis and affect tumor progression." (PMID 41296440, 2025). "Moreover, flow cytometric analysis showed a significant increase in apoptosis rates in the APOC2-silenced groups, further supporting the notion that APOC2 may act as a tumor promoter gene." (PMID 41296440, 2025). "Considering the normal expression of p300 and APOC2, as well as lactate metabolism in the liver, we cannot dismiss the possibility that lactylated APOC2 in liver cells could reach the surrounding tumor tissue alongside LDL/VLDL, which could potentially contribute to immune resistance." (PMID 38981044, 2024). "Therefore, the immunosuppressive tumor microenvironments in patients of the dominant group could be caused by the CD8-Tef-GZMA and CD8-Tef-APOC2 subpopulations." (PMID 36497182, 2022). "Emerging evidence indicates that apolipoprotein C2 (APOC2) lactylation enhances lipolysis to promote FFA release, correlating with tumor metastasis and immunotherapy resistance." (PMID 40849305, 2025). "Because APOC2 in lactylated status is more stable and mainly exists in the tumor interstitial fluid, anti‐APOC2K70‐lac Ab is sufficient to neutralize extracellular APOC2." (PMID 38981044, 2024). "By integrating proteomic and transcriptomics profiles of GC and PM samples, we reported that APOC2 cooperated with CD36 to regulate EMT process via PI3K/AKT/mTOR signaling, which eventually promoted tumor progression and PM in GC." (PMID 34459127, 2021). "Based on our enrichment analysis, we hypothesize that APOC2 may promote the malignant progression of ccRCC by activating the JAK/STAT signaling pathway, thereby enhancing tumor cell viability and growth." (PMID 41296440, 2025). "A significant correlation between APOC2 protein levels and total non‐histone Kla was observed, with substantially higher APOC2 protein levels evident in tumor samples than in adjacent normal tissues." (PMID 38981044, 2024). "In single-cell RNA-seq data, we found that, in some patients, the glutamine metabolism gene scores of tumor cells were significantly higher than those of CD8T cells, while decreased ratios of CD8-Tef-GZMA and suppressed tumor-killing activity of CD8-Tef-APOC2 were observed." (PMID 36497182, 2022).
tumor (continued). "The fact that some of these EV proteins (e.g., PBIP1 and APOC2), mRNAs (e.g., DLC1 and MTO1), and miRNA (e.g., hsa-miR-99a-5p and hsa-mir-203a-3p) are present in the EVs of EC or SI tumor patients, exclusively, suggests that they are able to fulfill that unique role." (PMID 36568159, 2022). "However, a subset of genes up-regulated in microglia/tumor co-culture was found to be exclusively related to the concurrent presence of astrocytes (APOE, APOC2, HLA-DRA)." (PMID 31186414, 2019). "Under a high lactate microenvironment, lactylated-APOC2 is secreted via paracrine signaling into the tumor microenvironment (TME), where it binds to highly expressed lipoprotein lipase (LPL) to form the complex that enhances TG hydrolysis, thereby producing FFA for tumor metabolism." (PMID 40849305, 2025). "A study found that APOC1, APOC2, APOC3, and APOC4 were expressed differently in tumor and non-tumor tissues in hepatocellular carcinoma." (PMID 38067270, 2023).
cancer (21 papers, 2016 to 2025). A tumor composed of atypical neoplastic, often pleomorphic cells that invade other tissues. "A comparison early-stage and late-stage CRC patients revealed 4 potential biomarkers associated with cancer progression, including C4B, C8A, APOC2, and IGHG2." (PMID 38911905, 2024). "Knockdown either APOC2 or CD36 inhibited the malignant phenotype of cancer cells, and delayed GC PM progression in murine GC models." (PMID 34459127, 2021). "Among them, a gradual increase from early-stage cancer to more advanced stages were strongest for APOC2 and IL8 genes followed by for SAA4 and OSM genes, whereas HIST1H1E, PF4V1, CXCL5, and IL2RA expression showed limited stage-wise upregulation." (PMID 33828156, 2021). "However, study toward the role of APOC2 in cancer is scarce." (PMID 34459127, 2021). "Moreover, APOC2 was proposed as a serum biomarker of other cancers." (PMID 30065196, 2018). "An overexpression of APOC2 and APOC3 was reported by some studies reviewed in this manuscript and has been investigated in other cancers." (PMID 39194522, 2024). "While the roles of specific APOs like APOC2, APOD, and APOM are still under investigation, continued research promises to deepen our understanding of how the APO family interacts with cancer." (PMID 38067270, 2023). "The CD8-Tef-APOC2 subpopulation, which was heavily infiltrated in the TME of the cancer-cell-dominant group, was characterized by the upregulation of the exogenous lipid metabolism and immunosuppressive pathways." (PMID 36497182, 2022). "In contrast to the relatively known roles of BIRC5, CENPF, and STMMN1 in malignancies, functions of APOC2 and HNRNPC genes in cancer cell are less well defined." (PMID 33828156, 2021). "Mechanistically, through interacting with CD36, ApoC2 induces the activation of the PI3K/AKT/mTOR signaling pathway, promoting the over-expression of EMT markers and confer mesenchymal phenotype of GC cells and eventually foster cancer metastasis." (PMID 36506554, 2022). "In addition, liver X receptor β (LXRβ) is overexpressed in PTC and induce the expression of its target genes including APOC1, APOC2 and APOE, which may activate lipid metabolism and protein synthesis, thus facilitating cancer cell proliferation." (PMID 36506554, 2022).
metabolic disorders (6 papers, 2019 to 2025). "The results suggest that adipose ApoC2 activation may offer an alternative strategy for controlling UCP1-mediated energy expenditure to combat metabolic disorders." (PMID 39798876, 2025).
infection (4 papers, 2011 to 2025). The state of being infected such as from the introduction of a foreign agent such as serum, vaccine, antigenic substance or organism. "ApoC2 is synthesized by the liver and is involved in triglyceride synthesis, but its role in infection remains speculative." (PMID 23198120, 2011). "As seen in infection with HCVcc (JFH1), expression of ApoA1, ApoA2, ApoC1, ApoC2, ApoC3 and ApoE enhanced the formation of infectious particles of TH/JFH1 and S310/JFH1 chimeric viruses." (PMID 25502789, 2014).
genetic disorder (1 paper, 2024). "APOC2 deficiency is a rare genetic disorder characterized by insufficient or absent levels of APOC2 protein." (PMID 38521668, 2024).
intestinal diseases (1 paper, 2024). "Various biomarkers, including blood amyloid A, apolipoprotein C2, and stool calprotectin, have been suggested as potential indicators for predicting intestinal diseases in neonates." (PMID 38398801, 2024).
neurological disease (1 paper, 2018). "The level of APOC2 was not different in the CSF proteome of patients with RRMS and other neurological disease controls." (PMID 30114292, 2018).
APOC2 also shares sentences with these, for which no sentence is quoted: diabetes (9 papers); cardiovascular disease (7); Insulin resistance (6); chronic kidney disease (3); colorectal cancer (3); Hepatic steatosis (3); myocardial infarction (3); angina pectoris (2); familial amyloidosis (2); familial hypercholesterolemia (2); nephrotic syndrome (2); ovarian carcinoma (2); respiratory distress syndrome (2); systemic amyloidosis (2); xanthoma (2); AA amyloidosis (1); AL amyloidosis (1); antibody deficiency against (1); aortic atherosclerosis (1); arteriosclerosis (1); autosomal recessive disease (1); bacterial infectious disease (1); behavioral disorders (1); bladder cancer (1); bladder urothelial carcinoma (1); Cachexia (1); central obesity (1); cervical squamous cell carcinoma (1); cholesterol ester storage disease (1); chronic pancreatitis (1).
A further 44 diseases each share a sentence with APOC2 in 1 paper.